BRAF (B-Raf proto-oncogene, serine/threonine kinase)
Diseases named in the same sentence as BRAF in open-access papers (continued):
Sharing a sentence is not in itself a finding about the gene and the disease.
melanoma (continued). "Vemurafenib is the first approved fragment based drug discovery for mutant BRAF melanoma." (PMID 35350751, 2022). "For growing-phase melanoma cases, medicinal treatments have been remarkably developed with the incorporation of immune inhibitor types and selective therapy such as BRAF and mitogen-activated protein kinase (MEK) inhibitors and programmed cell death ligand-1 (PDL-1) blockage." (PMID 35360535, 2022). "Several therapeutic options exist for patients with advanced BRAF-mutant melanoma." (PMID 35954369, 2022). "Importantly, a fibroblastic and remodeled ECM was observed in the tumoral stroma of melanoma tissue from Vemurafenib (BRAF inhibitor) treated patients." (PMID 36119516, 2022). "Thus, we can conclude that MICA secretion was low in BRAF-WT melanoma both in EVs, and as soluble protein." (PMID 36726591, 2022). "There was no clear relationship between either melanoma stage or BRAF/NRAS mutation status and the presence of TERT promoter variant T349C." (PMID 35494035, 2022). "In melanomas, tumor transformation is often driven by the dysregulation of the mitogen-activated-protein-kinase (MAPK)-proliferation signaling pathway as a consequence of BRAF and NRAS mutations seen in 50% and 20% of cases, respectively." (PMID 35326683, 2022). "Importantly, in paired biopsies obtained from patients with BRAF-mutant melanoma before treatment and after initiation of BRAF inhibitor therapy, the suppression of S6 phosphorylation was found to be predictive of improved progression-free survival." (PMID 36077374, 2022). "In BRAF-mutated melanoma cells, the inhibition of NAMPT, using FK866 and GMX1778, or its genetic knock-down, reduced cancer cell proliferation, both in vitro and in vivo, highlighting NAMPT as an actionable target for melanoma patients with BRAF mutations." (PMID 36077374, 2022). "Notably, miR-211-mediated DUSP6 downregulation resulted in an increased ERK5 phosphorylation and BRAF inhibitors resistance in melanoma." (PMID 35053510, 2022). "Furthermore, inactivation of Smarca4 delays tumor formation in a mouse melanoma model driven by oncogenic BRAF/inactivated PTEN." (PMID 35323214, 2022). "Low-CSD melanoma is likely to arise as a result of aberrations of BRAF mutation (45%) rather than RAS and NRAS mutations, which are identified in high-CSD exposure, in 15–30% and 15% of cases, respectively." (PMID 35334544, 2022). "What’s more, the inhibition of oxidative metabolism by BRAF in melanoma is an independent process." (PMID 36620597, 2022). "Preclinical studies also demonstrated that acquired resistance to BRAFi can be due to MAPK pathway and blocking this pathway may induce apoptosis in BRAF V600 mutant melanoma." (PMID 35954441, 2022). "However, recent findings have also identified a sub-group of melanomas, which are driven by BRAF mutants with low-activity and which consequently rely on CRAF signaling." (PMID 35883461, 2022). "The BRIM-8 trial of adjuvant vemurafenib in resected, BRAF V600 mutation-positive stage IIC-III melanoma did not meets its primary endpoint of RFS in patients with stage IIIC disease." (PMID 35538491, 2022). "Acquired resistance to common melanoma treatments, such as BRAF inhibitors, is inevitable." (PMID 35954441, 2022). "The present study describes the application of new and advanced approaches for identifying changes in chromatin accessibility that modulate gene expression and signaling pathway activities to promote MAPK pathway inhibitor resistance in BRAF-mutant melanoma cells." (PMID 35785205, 2022). "GT-7 and its original compound ACA-28 were shown to induce ERK-dependent apoptosis in melanoma cell lines, harboring oncogenic BRAF or NRAS mutation, but not in the normal melanocyte (NHEM)." (PMID 35203351, 2022).
melanoma (continued). "Even though included patients were treated in the adjuvant setting for melanoma, patient populations slightly differ since the studied treatments are applied for specific indications within adjuvant treatment (e.g., D + T for BRAF positive patients only, and nivolumab also for resected stage IV)." (PMID 36358844, 2022). "Tumor suppressors and oncogenes with a demonstrated role in melanoma tumorigenesis and progression lay on regions that are recurrently aneuploid, including the oncogenes BRAF (7q34) and MYC (8q24) and the tumor suppressors BAP1 (3p21), CDKN2A (9p21) and PTEN (10q23)." (PMID 36276131, 2022). "In addition, melanoma cells with BRAF-containing DMs harbor increased resistance towards dual BRAF and MEK inhibition." (PMID 36184613, 2022). "These genes are often mutated in melanomas, so the RAS-PTEN/BRAF axis is mostly abnormal." (PMID 36613640, 2022). "In melanomas lacking these common coding mutations (BRAF, NRAS, KRAS, HRAS, NF1, KIT, GNAQ, and GNA11), there is a high frequency of kinase fusions." (PMID 35974375, 2022). "While MEK inhibitors may fully block tumor proliferation in BRAF-dependent melanomas, RAS mutants are only partially inhibited." (PMID 35380338, 2022). "Interestingly, both compounds reduced the level of oncogenic BRAF in a dose-dependent manner in both melanoma cell lines." (PMID 36009541, 2022). "PD-L1+ PMN frequency was associated with worse patient survival only in BRAF wild type melanoma patients but not in BRAF mutated melanoma patients." (PMID 36016960, 2022). "This study resulted in the identification of new genes and signaling pathways that might be targeted to treat MEK or BRAF inhibitors resistant melanoma patients." (PMID 35785205, 2022). "Indeed, Gr1+ MDSCs have previously been reported to play a role in mediating stromal resistance to BRAF inhibition in a BRAFV600E-driven melanoma model." (PMID 34779486, 2022). "The MAPK pathway is also activated by NRAS mutations that are frequently found in several tumor types and in 15–20% of melanoma patients but not concomitant with BRAF mutations." (PMID 35495634, 2022). "It is also important that the BRAF-mutant melanomas may also develop PD-L1 gene amplification, which may result in immunoresistance, although it could increase sensitivity to ICIs targeting the PD-1/PD-L1 axis." (PMID 35628196, 2022). "Notably, pharmacological BRAF inhibition further stimulated ERBB3 signaling in YAP1-activated melanoma cells in line with a previous report, highlighting ERBB3 as a particularly relevant target in MAPKi-resistant melanoma cells with high YAP1 activity." (PMID 35798875, 2022). "In the past decade, two therapeutic strategies have significantly improved outcomes in MM: molecularly targeted therapy for BRAF-mutant melanoma and immune checkpoint inhibitors (ICIs) that are not mutation-specific." (PMID 36290885, 2022). "Notably, blue-grey peppering and white-scar areas were both observed more frequently in MAPK mutant melanomas (either NRAS or BRAF) than in WT." (PMID 35160279, 2022). "Finally, there are two new parts of this trial (parts 4 and 5), that aimed to use pembrolizumab plus trametinib for patients with solid tumors or BRAF wild-type melanoma, with results still pending publication." (PMID 36358912, 2022). "Interestingly, the combined treatment was strikingly effective, both in the BRAF inhibitor sensitive and in primary and acquired BRAF inhibitor resistant melanoma cell lines." (PMID 35563772, 2022). "Because melanoma cells lacking a BRAF mutation do not respond well to current KIs, we also contrast results between genomic subtypes of melanomas." (PMID 35560144, 2022).
melanoma (continued). "Moreover, it was shown that the use of MIM1-high and specific Mcl-1 inhibitor increased the level of Mcl-1 protein in BRAF-mutant amelanotic C32 melanoma cells with subsequent apoptosis induction." (PMID 36045272, 2022). "However, our results indicate that surrounding fibroblasts play an essential role in coordinating evasion of co-cultured BRAF-mut melanoma cells from both BRAF and combined BRAF/MEK inhibition in a SEMA6A-dependent manner." (PMID 35440004, 2022). "In melanoma, splice variants of BRAF lacking the RAS‐binding domain confer resistance to vemurafenib." (PMID 35593080, 2022). "Approximately half of all melanomas are BRAF mutants, and 20% are NRAS mutant." (PMID 34837846, 2022). "The coinhibition of BRAF and FAK has been used to block ERK reactivation in BRAF-mutant melanomas." (PMID 35163650, 2022). "According to these data, pre-treatment PD-L1+ PMN frequencies selectively predict patient clinical outcome and therapeutic response to nivolumab in melanoma patients without BRAF mutations." (PMID 36016960, 2022). "Combining these findings with the RNA‐seq results, we speculated that the anti‐BRAF‐mutant melanoma effect of lj‐2‐66 may be related to the induction of DNA damage." (PMID 35332658, 2022). "The rapid development of cSCC in vemurafenib-treated melanoma patients and the evidence that BRAF inactivation drives aneuploidy may suggest vemurafenib-dependent genomic instability." (PMID 35174094, 2022). "Vemurafenib, a second-generation selective small molecule inhibitor of RAF, is highly potent in inhibiting the activation of this pathway in BRAF V600E-mutant melanoma cells and thereby is highly effective in combating the growth of metastases in the melanoma patients (for review, see 2)." (PMID 35174094, 2022). "Besides the immunotherapy targets such as PD-1/PD-L1 and CTAL-4, the classic target genes in melanoma are BRAF- and MEK-related pathways." (PMID 35915735, 2022). "Malignant melanoma, however, can develop on non-UV-exposed skin, mucosal epithelium or uvea, and these melanoma types usually lack the characteristic BRAF mutation." (PMID 35628196, 2022). "For instance, in anti-PD-1 resistant BRAF-mutant melanoma models, concurrent treatment with dabrafenib and trametinib led to significantly enhanced tumor growth inhibition, increased CD8+ cytotoxic and CD4+ helper T cell infiltration, and an upregulation of MHC class I and II molecules." (PMID 35806358, 2022). "Fortunately, angiogenesis inhibitors might be suitable for BRAF-mutant melanoma patients with acquired resistance to BRAF/MEK inhibitors." (PMID 36588679, 2022). "Moreover, the COMBI-AD trial showed that D+T (Dabrafenib+Trametinib) adjuvant therapy is also currently recommended for BRAF-mutant stage III melanoma patients." (PMID 36678538, 2022). "However, reactivation of MAPK signalling was observed in approximately 70% of melanomas after treatment with BRAF inhibitors, MEK inhibitors, or both." (PMID 35335966, 2022). "As our in vivo model we chose D4M.3A murine melanoma cell line as it bears the BRAF V600E mutation and lack of melanin, which provides the black color of the tumor, as in the case of the B16-F10 melanoma model." (PMID 36168618, 2022). "To address whether BRAF inhibition induces SOX2 expression in melanoma, we treated A375, SK-MEL-5, and A2058 cells, which express BRAFV600E, with PLX4032 (vemurafenib) and GSK2118436 (dabrafenib), two selective BRAFi." (PMID 35944584, 2022). "In this study, we performed unbiased RNA-sequencing (RNA-seq) and assay for transposase-accessible chromatin with sequencing (ATAC-seq) to identify new targets and mechanisms that drive resistance to MAPK pathway inhibitors targeting BRAF and MAPK kinase (MEK) in BRAF-mutant melanoma cells." (PMID 35785205, 2022). "BRAF and NRAS gene mutations were also associated with shorter survival in melanomas." (PMID 35444210, 2022).
melanoma (continued). "BRAF mutations are highly prevalent in melanoma and found in 40–60% of cultured primary melanoma cells but are not sufficient for melanoma progression and development since they are found in benign nevi." (PMID 35495634, 2022). "The approval of BRAF-targeted therapies and immunotherapy and their subsequent rapid incorporation into standard of care resulted in a decline of nearly 8% in mortality rates across all stages of melanoma in the U.S. between 2013 and 2019." (PMID 36076924, 2022). "In order to investigate the role of ADCK2 in melanoma, we checked the endogenous mRNA expression levels of nine melanoma cell lines (BRAF and NRAS WT: MeWo, BRAF-mutated: WM2664, A375, HT144, SkMel28, C32 and NRAS-mutated: SkMel30, SkMel103, SkMel173) and normal human melanocytes (NHM)." (PMID 35205819, 2022). "AT-Rich Interaction Domain 1A (ARID1A) is one of the genes most commonly mutated in melanoma without presenting a mutation hotspot (i.e., V600 in BRAF)." (PMID 35565222, 2022). "Similarly, BRAF inhibitor PLX4720-resistant melanoma cells also exhibit increased glutaminolysis, mitochondrial biogenesis, and oxidative metabolism." (PMID 35011702, 2022). "A team under the same leadership performed another analysis of the efficacy of nivolumab and ipilimumab in patients depending on the presence or absence of BRAF mutations in previously untreated advanced melanoma." (PMID 36291906, 2022). "Subsequently, ddPCR analysis of a patient derived melanoma cell line (corresponding to a timepoint 12 months after liquid biopsy samples 4 and 9) confirmed the BRAF V600E mutation but not the NRAS Q61R mutation (ddPCR data not shown)." (PMID 35494035, 2022). "Therefore, resistance to BRAF inhibitors in SIRT6-haploinsufficient melanoma cells can be relieved by combinatory application of a clinically available IGF-1R inhibitor." (PMID 35372044, 2022). "A phase III double-blind placebo controlled randomized trial of dabrafenib with trametinib, an MEK inhibitor, was carried out for adjuvant therapy for patients with high chances of BRAF V600 mutant-positive stage III melanoma after surgical resection (COMBI-AD)." (PMID 36699049, 2022). "To test this, we stably expressed disease-representative MEK mutants (cancer-derived Q56P, K57N, and C121S; RASopathy-derived F53S and Y130C) in A375 melanoma cells harboring BRafV600E, and assessed their effects on the sensitivity of the tumor cells to BRaf- or MEK-inhibitors." (PMID 35831322, 2022). "There is no specific treatment for NSCLC patients carrying a BRAF mutation, even if in melanoma, BRAF inhibitors were demonstrated to prolong progression-free survival and survival." (PMID 36380085, 2022). "The phase III IMspire150 trial showed that treating BRAF V600‐mutant melanoma with atezolizumab, vemurafenib, and cobimetinib significantly increased PFS from 10.6 months with vemurafenib and cobimetinib to 15.1 months (HR, 0.78; 95%CI: 0.63, 0.97; p = 0.025) without obviously adding adverse events." (PMID 36254250, 2022). "Although human BRAF- and NRAS-mutated melanomas have been associated with an increased risk for liver metastases, this association was rather weak and until now it has not been shown that one of these main driver mutations is a key determinant of hepatic metastasis." (PMID 35109875, 2022). "Similarly, SRC inhibition also selectively sensitized de-differentiated melanomas to BRAF inhibition." (PMID 36271142, 2022). "However, the phase 2 trial of vemurafenib targeting BRAF-mutated PTC patients showed only a 38.5% response rate, which is considerably lower than that in patients with BRAF-mutated melanoma." (PMID 35600399, 2022).
melanoma (continued). "The clinical application of triplet therapies in the first-line metastatic setting has been limited by a lack of comparison to either single-agent anti-PD-1 or IPI + NIVO, which have since emerged as standards of care for both BRAF-mutant and wild-type melanoma." (PMID 35366166, 2022). "The first inhibitor of mutated BRAF (BRAFi), approved by the FDA (2011) and EMA (2012), was vemurafenib (PLX4032), and other drugs targeting BRAF were later approved, like dabrafenib (GSK2118436), with similar results in melanoma patients." (PMID 36726591, 2022). "Additionally, lncRNA-orilncl (the genetic target of RAS) was upregulated in BRAF mutant melanoma and promoted tumor cell proliferation and growth by regulating the RAS-RAF-MEK-ERK signaling pathway." (PMID 36601121, 2022). "In melanoma, especially BRAF and MEK-targeted therapy was proved to be beneficial." (PMID 35559262, 2022). "These mutations have important clinical significance since mutated BRAF protein is active as a monomer instead of dimer and the monomer conformation is the target for the binding of BRAF inhibitors, such as vemurafenib, dabrafenib and encorafenib, used in melanoma therapy." (PMID 35495634, 2022). "BRAF inhibitors have been a game changer in melanoma, but resistance became a problem." (PMID 34498671, 2022). "However, in human A375 melanoma xenografts in-vivo, the HP pyruvate-lactate exchange was increased after BRAF inhibition." (PMID 35327519, 2022). "However, despite the survival advantages observed with BRAF-targeted drugs versus chemotherapy, many melanoma patients progressed within 6-7 months, mainly due to ERK re-activation." (PMID 35814399, 2022). "In particular, evidence has been provided that BRAF-mutant tumors tend to metastasize more frequently and correlate with shorter overall survival in patients with advanced cancer than in those with BRAF wild-type melanoma." (PMID 36009541, 2022). "In contrast, 67% of melanoma patients have a mutation in KRAS, NRAS, BRAF, or NF1 genes (n = 471)." (PMID 35806358, 2022). "However, with only 46 patients across CheckMate 067 and 069 having BRAF mutant melanoma, the data are insufficient to evaluate the impact of PPI use on ICI efficacy based on BRAF mutation status." (PMID 35565428, 2022). "Finally, SEMA6A prediction of benefit from dual BRAF/MEK inhibition was investigated in melanoma cohort RECI2 (N = 14)." (PMID 35440004, 2022). "They found that younger age, lack of extracranial metastases, better Karnofsky performance status score, fewer melanoma brain metastases, as well as treatment with BRAF inhibitors, anti-PD1/CTLA4 therapies, or cytokine therapy were significantly associated with improved overall survival." (PMID 35311078, 2022). "We demonstrated that short-term treatment of mice with ARN22089 could prolong survival in a BRAF mutant autochthonous mouse model of melanoma." (PMID 35385746, 2022). "CIIs can achieve a more durable response in melanoma patients compared with BRAF-targeted therapy." (PMID 36499102, 2022). "Therefore, we chose lj‐2‐66 for follow‐up experiments to test its anti‐BRAF‐mutant melanoma activity and mechanism." (PMID 35332658, 2022). "About 50% of melanomas carry activating mutations in the BRAF oncogene and about 30% in the NRAS gene leading to overactivation of the mitogen-activated protein kinase (MAPK) pathway, making this signaling cascade a preferential target for melanoma treatment." (PMID 35884430, 2022). "Conversely, we next tested whether miR‐143‐3p or miR‐145‐5p inhibition can reverse the phenotypic pro‐fibrotic response induced by oncogenic BRAF inhibition in M238P melanoma cells." (PMID 35156321, 2022). "Finally, EVs produced by a melanoma cell line resistant to BRAF inhibition was also shown to carry increased levels of PD-L1." (PMID 36289847, 2022). "Interestingly, preclinical and clinical studies combining anti–PD-1/PD-L1 with BRAF/MEK inhibitors have demonstrated enhanced anti-melanoma responses and tolerability." (PMID 35515106, 2022).